TRIM77 (tripartite motif containing 77)
Synonyms: TRIM77P
Tractability: PROTAC: ubiquitination databases record sites on it.
Gene: Protein-coding gene on chromosome 11 (89,710,299 to 89,717,872, forward strand). Ensembl gene ENSG00000214414.
Gene Ontology:
Molecular function: ubiquitin protein ligase activity; metal ion binding; zinc ion binding
Biological process: innate immune response; regulation of gene expression
Cellular component: cytoplasm
Genetic constraint (gnomAD): Loss-of-function variants: 15 observed, 20.29 expected, observed/expected ratio (o/e) 0.74, 90% interval 0.49 to 1.14. The upper end of that interval is the gene's LOEUF score, 1.14, which puts it in group 4 of 6, group 1 being the genes least tolerant of losing a copy. Missense variants: 417 observed, 487.91 expected, observed/expected ratio (o/e) 0.85, 90% interval 0.79 to 0.93. Synonymous variants: 150 observed, 165.64 expected, observed/expected ratio (o/e) 0.91, 90% interval 0.79 to 1.04.
Homologues: Orthologues: chimpanzee TRIM77 (98% identical), macaque TRIM77 (94% identical), rabbit TRIM77 (66% identical), dog TRIM77 (62% identical), pig TRIM77 (62% identical). Paralogues in human: TRIM43 (48% identical), TRIM43B (48% identical), TRIM51 (44% identical), TRIM49B (44% identical), TRIM49 (43% identical), TRIM49C (43% identical), TRIM51G (43% identical), TRIM49D1 (42% identical), TRIM49D2 (42% identical), TRIM64 (41% identical), TRIM64B (41% identical), TRIM64C (41% identical), and 68 more.
Diseases named in the same sentence as TRIM77 in open-access papers:
TRIM77 is named in the same sentence as 5 diseases in open-access papers, as found by Europe PMC text mining. Sharing a sentence is not in itself a finding about the gene and the disease. The quoted sentences say what the papers report.
colorectal cancer (1 paper, 2021). A primary or metastatic malignant neoplasm that affects the colon or rectum. "In contrast, we performed analysis with the primary colorectal cancer tissue in this study and identified TRIM77 and a series of CNV changes as the prognostic factors, which was distinct from previous reports." (PMID 34993129, 2021).
ischemic heart disease (1 paper, 2020). "Moreover, studies have shown that TRIM77 may protect against ischemic heart disease-associated myocardial infarction and the recombinant human TRIM77 protein was also shown to have cardioprotective effects against I/R injury." (PMID 32463795, 2020).
cancer (1 paper, 2021). A tumor composed of atypical neoplastic, often pleomorphic cells that invade other tissues. "The fact that TRIM77 mutations were only present in primary cancer tissues of patients with liver metastasis suggested that TRIM77 mutations may correlate with subpopulations of primary cancer cells that migrate to liver, and therefore its mutations could be used as indicators for liver metastasis." (PMID 34993129, 2021).
TRIM77 also shares sentences with these, for which no sentence is quoted: metastasis (1 paper); myocardial infarction (1).